HEYL (hes related family bHLH transcription factor with YRPW motif like)
Description:
Downstream effector of Notch signaling which may be required for cardiovascular development (By similarity). Transcriptional repressor which binds preferentially to the canonical E box sequence 5'-CACGTG-3' (By similarity). Represses transcription by the cardiac transcriptional activators GATA4 and GATA6.
Synonyms: bHLHb33; HRT3; HEY3; HESR3
Tractability: PROTAC: ubiquitination databases record sites on it.
Gene: Protein-coding gene on chromosome 1 (39,623,435 to 39,639,643, reverse strand). Ensembl gene ENSG00000163909.
Subcellular location: Nucleus
Subcellular location (Human Protein Atlas): Nucleoli fibrillar center
Pathways (Reactome):
Disease: Constitutive Signaling by NOTCH1 HD+PEST Domain Mutants; Constitutive Signaling by NOTCH1 PEST Domain Mutants
Signal Transduction: NOTCH1 Intracellular Domain Regulates Transcription; NOTCH3 Intracellular Domain Regulates Transcription
Cell-Cell communication: Regulation of CDH11 gene transcription
Gene Ontology:
Molecular function: AF-1 domain binding; DNA-binding transcription factor activity; DNA-binding transcription factor activity, RNA polymerase II-specific; DNA-binding transcription repressor activity, RNA polymerase II-specific; protein binding; RNA polymerase II cis-regulatory region sequence-specific DNA binding; DNA binding; DNA-binding transcription activator activity, RNA polymerase II-specific; protein dimerization activity; protein homodimerization activity; sequence-specific DNA binding
Biological process: negative regulation of androgen receptor signaling pathway; negative regulation of DNA-templated transcription; Notch signaling pathway; positive regulation of transcription by RNA polymerase II; anterior/posterior pattern specification; aortic valve morphogenesis; atrioventricular valve morphogenesis; cardiac epithelial to mesenchymal transition; cardiac ventricle morphogenesis; endocardial cushion morphogenesis; epithelial to mesenchymal transition involved in endocardial cushion formation; mesenchymal cell development; negative regulation of transcription by RNA polymerase II; outflow tract morphogenesis; positive regulation of neuron differentiation; pulmonary valve morphogenesis; regulation of neurogenesis; ventricular septum morphogenesis; anatomical structure morphogenesis; cellular response to BMP stimulus; circulatory system development; glomerulus development; proximal tubule development; regulation of DNA-templated transcription
Cellular component: nucleus; chromatin; cytoplasm; nucleoplasm
Genetic constraint (gnomAD): Loss-of-function variants: 12 observed, 15.55 expected, observed/expected ratio (o/e) 0.77, 90% interval 0.49 to 1.25. The upper end of that interval is the gene's LOEUF score, 1.25, which puts it in group 5 of 6, group 1 being the genes least tolerant of losing a copy. Missense variants: 417 observed, 407.87 expected, observed/expected ratio (o/e) 1.02, 90% interval 0.94 to 1.11. Synonymous variants: 158 observed, 157.7 expected, observed/expected ratio (o/e) 1, 90% interval 0.88 to 1.14.
Homologues: Orthologues: chimpanzee HEYL (99% identical), macaque HEYL (95% identical), dog HEYL (87% identical), pig HEYL (85% identical), guinea pig HEYL (83% identical), rat Heyl (79% identical), rabbit HEYL (78% identical), mouse Heyl (78% identical), zebrafish heyl (42% identical), Drosophila melanogaster dpn (18% identical), Drosophila melanogaster Sidpn (17% identical), Drosophila melanogaster hry (17% identical), and 15 more. Paralogues in human: HEY1 (43% identical), HEY2 (42% identical), HELT (21% identical), HES1 (20% identical), BHLHE41 (20% identical), HES4 (20% identical), BHLHE40 (19% identical), HES6 (17% identical), HES2 (15% identical), HES5 (14% identical), HES7 (13% identical), HES3 (12% identical).
Diseases named in the same sentence as HEYL in open-access papers:
HEYL is named in the same sentence as 43 diseases in open-access papers, as found by Europe PMC text mining. Sharing a sentence is not in itself a finding about the gene and the disease. The quoted sentences say what the papers report.
breast carcinoma (10 papers, 2014 to 2024). "However, HEYL is the only Notch downstream target gene that is associated with the expression of the Notch ligand, Jagged, in breast cancer tissues." (PMID 33520697, 2020). "Increased HEYL expression has been associated with neovascularization in breast cancer." (PMID 28423742, 2017). "Blocking HEYL’s angiogenesis-promoting function in both tumor cells and tumor-associated endothelium may enhance efficacy of therapy targeting the tumor vasculature in breast cancer." (PMID 33520697, 2020). "The results showed that endothelial cells in tumors are specifically dominated by HMGA1 and HEYL, both of which have been found as promoters of neoangiogenesis in breast cancers." (PMID 38414027, 2024). "NOTCH3 is very weakly expressed in breast cancer cells, which prevents tumor occurrence through HeyL-mediated inhibition of Mybl2 (an important cell cycle regulator), and is related to good prognosis." (PMID 38164285, 2024). "Altogether, these data, show that Notch3, in breast cancer cells, induces a strong expression of HeyL that leads to downregulation of Mybl2, which leads to decreased proliferation." (PMID 36854682, 2023). "Elevated HeyL levels have been discovered in breast cancer, and HeyL transgenic mice display accelerated mammary gland epithelial proliferation, eventually leading to breast cancer." (PMID 35096586, 2021). "In this paper, we present evidence that overexpression of HEYL in breast carcinoma cells elicits a response in both tumor epithelial and endothelial cells that promotes angiogenesis." (PMID 33520697, 2020). "We also provided evidence that the expression of HEYL in tumor endothelial cells is potentially important for angiogenesis in breast cancer." (PMID 33520697, 2020). "High HEYL expression was found to be present in about 40% of breast cancers—a pattern consistent with enhanced Notch signaling in breast cancer." (PMID 33520697, 2020). "HEYL is the only Notch downstream target gene that correlated to the expression of the Notch ligand, Jagged, in breast cancer tissues." (PMID 33520697, 2020). "We reported that HEYL is overexpressed in approximately 40% of breast cancer epithelial cells, and HEYL promoted breast cancer development by binding to TGFβ-activated Smads and inhibiting TGFβ activity." (PMID 33520697, 2020). "We have also shown previously that HEYL is a direct transcriptional target of Notch in breast cancer cells." (PMID 33520697, 2020). "In 2004, we reported the discovery of HEYL as an overexpressed transcript through SAGE analysis of enriched populations of breast cancer endothelial cells from primary tumors." (PMID 33520697, 2020). "We had previously reported that serial analysis of gene expression (SAGE) profiles showed that HEYL is upregulated 20-fold in tumor endothelial cells of breast cancer compared to EC from normal breast." (PMID 33520697, 2020). "This show that HeyL is a direct target of Notch3 in breast cancer cell lines." (PMID 36854682, 2023). "We previously identified HEYL, a downstream target of Notch signaling, as an overexpressed gene in both breast cancer cells and as a tumor endothelial marker, suggesting that HEYL overexpression in both compartments may contribute to neoangiogenesis." (PMID 33520697, 2020). "Here, our data suggest a Notch-HEYL-angiogenic factor axis in breast cancer." (PMID 33520697, 2020). "In this paper, using engineered mouse and human model systems, we investigated whether HEYL is a key regulator of Notch-mediated angiogenesis in both epithelial and endothelial compartments in breast cancer." (PMID 33520697, 2020). "Thus, HeyL-/- mice showed impaired vessel outgrowth in the neonatal retina, while the growth of mammary tumor cells E0771 was retarded in syngeneic HeyL-/- mice compared to wild type C57/Bl6 mice." (PMID 33520697, 2020). "Furthermore, HeyL+/+ mice supported the growth of syngeneic E0771 mouse mammary tumors better than HeyL-/- mice." (PMID 33520697, 2020).
breast carcinoma (continued). "HEYL (hairy/enhancer-of-split related with YRPW motif) is a known transcriptional target of the Notch pathway, and its overexpression has been shown in breast cancer." (PMID 36476410, 2022). "We tested the effect of HEYL expression on cytokine gene expression in a second breast cancer cell line, MDA-MB-231, with shRNAs mediating downregulation of endogenous HEYL." (PMID 33520697, 2020). "While in breast cancer, Notch pathway inhibits TGF-β signaling through HEYL-mediated crosstalk, promoting initiation of breast cancer." (PMID 25477004, 2014). "The breast cancer pathway was further activated through the FGF18, HEYL, and WNT11 genes." (PMID 37887323, 2023).
gastric cancer (5 papers, 2020 to 2023). A primary or metastatic malignant neoplasm involving the stomach. "In conclusion, the HEYL is a potential prognostic and diagnostic biomarker for gastric cancer, and high expression of HEYL correlates with the activation of oncogenic signaling pathways in tumor." (PMID 32463580, 2020). "Furthermore, CDH11 was regulated by HEYL and rescued oncogenic behavior in HEYL deficient gastric cancer cells." (PMID 32463580, 2020). "Our findings not only identified the close relationship between TFs and TME phenotype, but also emphasized the crucial importance of TFs, especially HEYL, which could be identified as a candidate biomarker to evaluate prognostic risk and therapeutic effect in gastric cancer." (PMID 32463580, 2020). "A transcription factor, HEYL (Hes Related Family BHLH Transcription Factor With YRPW) included in our list was suggested previously as a potential prognostic marker for gastric cancer." (PMID 37296997, 2023). "Among them, HEYL, MMP7, THBS1, and KRT17 are not only highly expressed in gastric cancer, but are also independent prognostic risk factors for gastric cancer." (PMID 34157940, 2021). "Studies have shown that the HEYL gene is significantly increased in patients with gastric cancer, usually showing a poor prognosis." (PMID 34157940, 2021). "We first utilized two independent siRNAs targeting HEYL and found knockdown of HEYL markedly restrained proliferation and migration of these gastric cancer cells." (PMID 32463580, 2020). "We also uncovered HEYL represents a promising diagnostic biomarker, compared with traditional biomarker CA19‐9 in gastric cancer recurrence." (PMID 32463580, 2020). "To evaluate the contributions of HEYL for gastric cancer progression, we conducted HEYL knockdown AGS cells to undergo RNA sequencing (RNA‐seq) technology." (PMID 32463580, 2020). "Knockdown of HEYL prominently abrogated the tendency of cell proliferation, migration, and progression in gastric cancer." (PMID 32463580, 2020). "We first identified HEYL was upregulated in gastric cancer tissues and correlated with poor outcomes for GC patients." (PMID 32463580, 2020). "Our former investigations have revealed the correlation between HEYL expression with TME components and clinical significations in gastric cancer, whereas absently known about the detail molecular function of HEYL in gastric cancer cell behaviors." (PMID 32463580, 2020). "Collectively, these results manifest that HEYL promotes gastric cancer cell metastasis in vitro and growth both in vitro and in vivo." (PMID 32463580, 2020). "Collectively, these data demonstrate that CDH11 was upregulated in gastric cancer and as an oncogene to promote gastric cancer progression via transcriptional regulation by HEYL." (PMID 32463580, 2020). "Consistently, overexpression of HEYL strikingly accelerated the gastric carcinoma development through activating oncogenic signaling pathways and transcriptional activation of cadherin 11 (CDH11)." (PMID 32463580, 2020). "High expression of HEYL has been shown to accelerate gastric carcinoma development." (PMID 36131795, 2022). "In summary, HEYL, MMP7, THBS1, and KRT17 are not only highly expressed in gastric cancer, but also associated with poor prognosis and may be potential prognostic biomarkers." (PMID 34157940, 2021). "Our data highlighted that TME‐related TFs, especially HEYL, may represent a potentially promising target of diagnosis and clinical interventions for gastric cancer patients." (PMID 32463580, 2020). "We carried out a combination of transcriptomic analysis for TME subtypes estimation on TCGA‐STAD cohort and revealed a functional TME regulator HEYL which correlated with stromal component accumulation and activation of cancer‐related signatures in gastric cancer." (PMID 32463580, 2020). "Notably, we found HEYL is upregulated and correlated with dismal prognosis in gastric cancer patients." (PMID 32463580, 2020).
gastric cancer (continued). "Taken together, these data suggest CDH11 as a downstream target of HEYL in gastric cancers." (PMID 32463580, 2020). "In summary, we precisely demonstrated a quantified TME infiltration pattern remodeling by TFs and found HEYL could represent a potentially prognostic and therapeutic target in gastric cancer." (PMID 32463580, 2020). "HEYL was regularly high expressed in gastric cancer and correlated with patients’ poor prognosis." (PMID 32463580, 2020). "Our findings demonstrated the important roles of HEYL in GC progression and indicated HEYL represents a potential prognostic and therapeutic target in gastric cancer." (PMID 32463580, 2020). "It was finally confirmed that HEYL, MMP7, THBS1, and KRT17 may be potential biomarkers of gastric cancer." (PMID 34157940, 2021). "The mode of action of HEYL on gastric cancer has not yet been clearly studied, and further proof is needed in the future." (PMID 34157940, 2021). "HEYL could also form heterodimeric complexes with HES1, an oncogene in many cancer types including gastric cancer, to regulate gene expression under transcription level." (PMID 32463580, 2020). "Intersection genes TREM2, CTHRC1, BGN, NOX4, GPX3, HEYL, and SFRP4 from the GSE72305 and GSE103236 datasets, which were differentially expressed in the normal gastric mucosa than in gastric cancer cells and in lymph node free to lymph node metastatic GC." (PMID 33976737, 2021).
prostate carcinoma (4 papers, 2021 to 2024). A carcinoma that arises from epithelial cells of the prostate gland. "Module 2 includes COL3A1, COL5A2, and NOTCH3, which have been reported to be associated with metastasis in prostate cancer, as well as HEYL, STMN2, and ASPN, which have been implicated in prostate cancer progression." (PMID 39347576, 2024). "HEYL-aromatase axis promotes CSCs via endogenous estrogen-induced autophagy in castration-resistant prostate cancer." (PMID 38025763, 2023). "HeyL overexpression increased endogenous estradiol levels and estrogen receptor-α (ERα) transcriptional activity by upregulating CYP19A1 expression, which encodes aromatase, enhancing prostate cancer stem cell (PCSC) properties in PC3 cells." (PMID 35096586, 2021).
colon cancer (3 papers, 2023 to 2024). "In colon cancer, Sarah and colleagues reported that HEYL inhibits the intravasation of metastatic CRC cells in vivo, hence negatively regulating metastasis formation." (PMID 39247594, 2024).
colorectal cancer (3 papers, 2019 to 2023). A primary or metastatic malignant neoplasm that affects the colon or rectum. "To investigate whether HEYL expression is associated with metastasis formation in colorectal cancer patients, we analyzed publicly available datasets for correlation between HEYL RNA expression levels, OS and metastatic cancer stage and compared HEYL RNA expression in metastatic and primary lesions." (PMID 31796022, 2019). "In vivo, HEYL modulates metastasis-forming capacity of spheroid cells derived from colorectal cancer patients." (PMID 37397391, 2023). "To address this question, we overexpressed HEYL in patient-derived colorectal cancer cells and assessed the impact of HEYL overexpression on metastasis formation utilizing xenotransplantation models in NSG mice which allows addressing different steps of the metastatic cascade." (PMID 31796022, 2019).
lung carcinoma (3 papers, 2021 to 2023). "In lung cancer, miR-665 can promote invasion and migration by targeting HEYL, a gene that encodes a transcription factor that inhibits Notch signaling, which suppresses p38 MAPK activity via induction of MKP-1." (PMID 37894282, 2023). "MiR-665 released from EVs can target HEYL, a transcription factor acting downstream of Notch, and by doing so promote lung cancer cell invasion and migration." (PMID 37894282, 2023). "By several lines of evidence, we confirmed that HEYL is a novel target of miR-665 in lung cancer cells." (PMID 34349799, 2021). "In summary, the present study highlights the role of exosomal miR-665 in promoting lung cancer cell invasion and metastasis by directly repressing Notch target gene HEYL." (PMID 34349799, 2021). "As a consequence, exosomal miR-665 promoted lung cancer cell invasion and migration by targeting Notch downstream transcription factor HEYL." (PMID 34349799, 2021). "Consequently, exosomal miR-665 can regulate the expression of HEY-like protein (HEYL), a downstream transcription factor of Notch pathway and promote lung cancer cell invasion and migration." (PMID 37371664, 2023). "To determine the clinical relevance of the lncRNA SCIRT/miR-665/HEYL pathway, we analyzed The Cancer Genome Atlas (TCGA) database and identified significant upregulation of SCIRT and miR-665 and downregulation of HEYL in lung cancer tissues." (PMID 34349799, 2021).
Ageusia (1 paper, 2022). A rare condition that is characterized by a complete loss of taste function of the tongue. "The association between the high frequency of partial-methylated HeyL promoter on the clinical-pathological findings in COVID-19 patients was clearly observed as the worst clinical outcomes including severe pneumonia, fever, dry cough, and ageusia and anosmia." (PMID 35655915, 2022). "Previously, we may suggest that the high frequency of partial-methylated HeyL promoter in aging patients has been implicated in the susceptibility to SARS-CoV-2 and its related severe illness including dry cough, anosmia and ageusia, and severe pneumonia." (PMID 35655915, 2022).
Anosmia (1 paper, 2022). An inability to perceive odors. "Statistical analysis of our data showed that partial-methylated of HeyL promoter increased the risk of severe pneumonia 5.66 times (P = 0.0513), fever 10 times (P = 0.0246), anosmia/ageusia 7.5 times (P = 0.0278), and dry cough 10.55 times (P = 0.0140)." (PMID 35655915, 2022). "Also, we observed that the frequency of partial-methylated HeyL promoter was higher in COVID-19 patients and associated with aging, fever, severe pneumonia, ageusia/anosmia, and dry cough compared to control healthy subjects." (PMID 35655915, 2022).
chronic lung disease (1 paper, 2021). According to the definitions of the American and British Thoracic Societies, including pulmonary functional tests, X-rays, and CT scans for items such as fibrosis, bronchiectasis, bullae, emphysema, nodular or lymphomatous abnormalities. "Therefore, future studies are required to explore the role of HEYL in regulating these processes during health and in the context of chronic lung disease." (PMID 34831437, 2021).
chronic obstructive pulmonary disease (1 paper, 2021). A chronic and progressive lung disorder characterized by the loss of elasticity of the bronchial tree and the air sacs, destruction of the air sacs wall, thickening of the bronchial wall, and mucous accumulation in the bronchial tree. "In addition, we observed decreased expression of HEYL in HBECs from donors with chronic obstructive pulmonary disease (COPD) vs. normal donors which correlates with the impaired differentiation capacity of COPD cells." (PMID 34831437, 2021).